RAD54L2 (RAD54 like 2)
Description:
Helicase that modulates androgen receptor (AR)-dependent transactivation in a promoter-dependent manner (By similarity). May stimulate the release of RNA polymerase II, that has paused near the transcription start sites of AR-targeted genes and unwind R-loops formed at these sites; R-loops result from the hybridization of the short RNA strand nascently synthesized by the paused RNA polymerase II molecule and the DNA template. May also stimulate double-strand break formation by TOP2B, which appears important for transcriptional output. Not able to remodel mononucleosomes in vitro (By similarity).
Synonyms: ARIP4; KIAA0809; SRISNF2L; HSPC325
Tractability: PROTAC: UniProt records ubiquitination sites on it; ubiquitination databases record sites on it.
Gene: Protein-coding gene on chromosome 3 (51,538,666 to 51,668,667, forward strand). Ensembl gene ENSG00000164080.
Subcellular location: Nucleus; Chromosome
Subcellular location (Human Protein Atlas): Nucleoplasm; Cytosol
Gene Ontology:
Molecular function: DNA/RNA helicase activity; protein binding; ubiquitin protein ligase activity; ATP hydrolysis activity; ATP-dependent chromatin remodeler activity; transcription coregulator activity; ATP binding; catalytic activity
Biological process: R-loop processing; transcription elongation by RNA polymerase II; chromatin organization
Cellular component: chromatin; chromosome; nucleus
Genetic constraint (gnomAD): Loss-of-function variants: 24 observed, 127.26 expected, observed/expected ratio (o/e) 0.19, 90% interval 0.14 to 0.26. The upper end of that interval is the gene's LOEUF score, 0.26, which puts it in group 1 of 6, group 1 being the genes least tolerant of losing a copy. Missense variants: 1,347 observed, 1,858.6 expected, observed/expected ratio (o/e) 0.72, 90% interval 0.69 to 0.76. Synonymous variants: 626 observed, 723.05 expected, observed/expected ratio (o/e) 0.87, 90% interval 0.81 to 0.93.
Homologues: Orthologues: chimpanzee RAD54L2 (99% identical), rabbit RAD54L2 (98% identical), guinea pig RAD54L2 (97% identical), dog RAD54L2 (97% identical), pig RAD54L2 (96% identical), mouse Rad54l2 (96% identical), rat Rad54l2 (96% identical), macaque RAD54L2 (90% identical), tropical clawed frog rad54l2 (65% identical), zebrafish rad54l2 (58% identical), Drosophila melanogaster CG4049 (36% identical), Caenorhabditis elegans rad-54.L2 (27% identical). Paralogues in human: ATRX (21% identical), EP400 (18% identical), SRCAP (18% identical), CHD2 (17% identical), CHD5 (17% identical), CHD9 (17% identical), CHD1 (16% identical), CHD7 (16% identical), CHD3 (16% identical), ERCC6 (16% identical), CHD4 (16% identical), SMARCA4 (16% identical), and 18 more.
Diseases named in the same sentence as RAD54L2 in open-access papers:
RAD54L2 is named in the same sentence as 23 diseases in open-access papers, as found by Europe PMC text mining. Sharing a sentence is not in itself a finding about the gene and the disease. The quoted sentences say what the papers report.
gastrointestinal stromal tumor (2 papers, 2022 to 2025). "RAD54L2 was associated with poor clinical outcomes in gastrointestinal stromal tumors and in a pediatric AML cohort treated with etoposide." (PMID 39870965, 2025). "Only RAD54L2 has been found to affect gastrointestinal stromal tumors, and the expression of RAD54L2 has a shorter overall survival time." (PMID 36384536, 2022).
Ataxia (1 paper, 2023). Ataxia refers to impaired coordination of voluntary muscle movement. "Since TDP2 gene mutations have been linked to hereditary neurological disease in individuals with seizures, ataxia, and intellectual disability, we speculate that RAD54L2 may protect against neurological disorders." (PMID 38055822, 2023).
COVID-19 (1 paper, 2025). A disease caused by infection with severe acute respiratory syndrome coronavirus 2. "The hypermethylated genes with lowest p-values for hospitalized COVID-19 patients at inclusion (T1) and at 6 weeks post-inclusion (T2) versus HCs included NXN, SLC2A12, RAD54L2, GIMAP5, and PPP2R5C, while the top five hypomethylated genes with lowest p-value were, LOC101928650, DLX5." (PMID 41227320, 2025).
lung carcinoma (1 paper, 2022). "In subjects aged ≤ 59 years, correlations of rs11720298, rs4687592 and rs9864693 in RAD54L2 with the susceptibility to lung cancer were also positive at a prior probability level of 0.1." (PMID 36384536, 2022). "The study aimed to assess the correlation between single nucleotide polymorphisms (SNPs) in DNA repair gene (GTF2H1 and RAD54L2) and the risk of lung cancer." (PMID 36384536, 2022). "In our research, we found that RAD54L2 rs9864693 was associated with an increased risk of lung cancer, especially in subjects aged ≤ 59 years." (PMID 36384536, 2022). "Especially, among subjects aged ≤ 59 years, RAD54L2 rs11720298 was related to a reduced susceptibility to lung cancer, while the risk-increasing associations were found for RAD54L2 rs4687592, RAD54L2 rs9864693 and GTF2H1 rs4150667." (PMID 36384536, 2022). "RAD54L2 rs9864693 GC genotype increased the risk of lung cancer (OR = 1.33, 95%CI: 1.01–1.77, p = 0.045)." (PMID 36384536, 2022). "In our research, we found that RAD54L2 rs9864693 was related to an increased risk of lung cancer in the Chinese Han population." (PMID 36384536, 2022). "Here, we first displayed the genetic association of RAD54L2 polymorphisms with the susceptibility to lung cancer in the Chinese Han population." (PMID 36384536, 2022). "Here, nine polymorphisms in GTF2H1 and RAD54L2 were selected and genotyped to explore their impact on the risk of lung cancer in the Chinese Han population." (PMID 36384536, 2022). "In the follow-up studies, we will improve relevant information and adjust risk factors to further analyze the correlation of GTF2H1 and RAD54L2 with the risk of lung cancer." (PMID 36384536, 2022). "The influence of GTF2H1 and RAD54L2 polymorphisms on lung cancer susceptibility was assessed using logistic regression analysis by calculating odds ratios (ORs) and their corresponding 95% confidence intervals (CIs)." (PMID 36384536, 2022). "Our study first revealed that RAD54L2 rs9864693 was associated with an increased risk of lung cancer in the Chinese Han population." (PMID 36384536, 2022). "Besides, an increased risk of lung cancer was observed for RAD54L2 rs4687592 in drinkers (OR = 2.54, p = 0.034)." (PMID 36384536, 2022). "RAD54L2 rs4687592 was associated with an increased risk of lung cancer in drinkers." (PMID 36384536, 2022). "Besides, the increased risk of lung cancer was observed for RAD54L2 rs4687592 in drinkers." (PMID 36384536, 2022). "In genotype model, subjects with RAD54L2 rs9864693 GC heterozygote genotype might have an increased risk of lung cancer compared with individuals with GG wild-type genotype (crude analysis: OR = 1.33, 95%CI: 1.01–1.76, p = 0.046; adjusted analysis: OR = 1.33, 95%CI: 1.01–1.77, p = 0.045)." (PMID 36384536, 2022). "Stratified analysis found that associations of RAD54L2 rs11720298, RAD54L2 rs4687592, RAD54L2 rs9864693 and GTF2H1 rs4150667 with lung cancer risk were found in subjects aged ≤ 59 years." (PMID 36384536, 2022). "Five SNPs in GTF2H1 and four SNPs in RAD54L2 in 506 patients with lung cancer and 510 age-and gender-matched healthy controls were genotyped via the Agena MassARRAY platform." (PMID 36384536, 2022). "Associations between RAD54L2 and GTF2H1 polymorphisms and the risk of lung cancer were evaluated under different genetic models." (PMID 36384536, 2022). "Besides, RAD54L2 rs11720298 was related to a reduced susceptibility to lung cancer in subjects aged ≤ 59 years, non-smokers and drinkers, while a risk-increasing association was found between rs4687592 and lung cancer risk in subjects aged ≤ 59 years and drinkers." (PMID 36384536, 2022). "In non-smokers and drinkers, the protective risk effect of RAD54L2 rs11720298 on the occurrence of lung cancer was observed, respectively." (PMID 36384536, 2022). "This study may increase the understanding of the effect of RAD54L2 and GTF2H1 polymorphisms on lung cancer occurrence." (PMID 36384536, 2022).
lung carcinoma (continued). "Our finding will provide evidence that age, BMI, smoking, and drinking might be associated with the effects of RAD54L2 and GTF2H1 variants on lung cancer susceptibility." (PMID 36384536, 2022). "This study may increase the understanding the effects of of RAD54L2 and GTF2H1 polymorphisms on the occurrence of lung cancer." (PMID 36384536, 2022). "However, the role of RAD54L2 gene in the occurrence and development of lung cancer needs to be further clarified." (PMID 36384536, 2022). "However, the effect of the RAD54L2 gene on the occurrence and development of lung cancer is unknown." (PMID 36384536, 2022). "Moreover, an association of RAD54L2 rs11720298 with the risk of lung cancer in non-smokers and drinkers was significant at a prior probability level of 0.1." (PMID 36384536, 2022). "Among non-smokers and drinkers, the protective effects of RAD54L2 rs11720298 (OR = 0.62, p = 0.011; and OR = 0.17, p = 0.008) on the occurrence of lung cancer were observed." (PMID 36384536, 2022). "Precisely, a protective effect of RAD54L2 rs11720298 on the occurrence of lung cancer was observed in non-smokers and drinkers." (PMID 36384536, 2022).
myopia (1 paper, 2024). "The overall categories in the differentially expressed genes during myopia onset and progression share only three genes in retina: LONRF1, RAD54L2 and DUSP4." (PMID 39028695, 2024).
skin cutaneous melanoma (1 paper, 2023). "Interestingly, expression of Rad54l2 in skin cutaneous melanoma metastasis is higher than that in primary sites." (PMID 37061606, 2023).
stomach adenocarcinoma (1 paper, 2023). "As shown in, among 38 cancer types, the Rad54l2 was significantly low-expressed in 10 cancers, except for stomach adenocarcinoma." (PMID 37061606, 2023).
cancer (4 papers, 2022 to 2025). A tumor composed of atypical neoplastic, often pleomorphic cells that invade other tissues. "We utilized the cancer genome atlas (TCGA) online database to determine the mRNA of Rad54l2." (PMID 37061606, 2023). "Finally, we investigated Rad54l2 expression in many malignant tumors, including RCC and evaluated its role in RCC through bioinformatic analysis." (PMID 37061606, 2023). "Rad54 like 2 (Rad54l2) which might be one of key effector proteins of DNA damage mediated by estrogen was downregulated in numerous cancers, however, its role in epidemiological characteristics of Xp11.2 tRCC was needed to further study." (PMID 37061606, 2023). "In Xp11.2 tRCC and HK-2 cells after estrogen treatment, Rad54l2 was downregulated, and GSEA showed that pathways significantly enriched in DNA damage repair and cancer related clusters after estrogen treated, as well as GO and KEGG analysis." (PMID 37061606, 2023). "RAD54L2 resolves TOP2-DNA adducts and protects cells from anti-cancer drugs such as etoposide." (PMID 38055822, 2023).
tumor (4 papers, 2018 to 2025). "As RAD54L2-mediated TOP2cc resolution could represent a mechanism for intrinsic or acquired tumor resistance to chemotherapies including TOP2 poisons, it represents a potential biomarker and a candidate target for anticancer drug discovery." (PMID 38055822, 2023).
RAD54L2 also shares sentences with these, for which no sentence is quoted: acute myeloid leukemia (1 paper); breast carcinoma (1); endometrial cancer (1); gestational diabetes mellitus (1); hepatocellular carcinoma (1); hereditary neurological disease (1); hypopharyngeal squamous cell carcinoma (1); Intellectual disability (1); neurological disorders (1); osteoarthritis (1); osteosarcoma (1); ovarian carcinoma (1); renal cell carcinoma (1); virus infection (1).